Y_RNA (Y RNA )
Gene: Miscellaneous RNA gene on chromosome 4 (52,786,537 to 52,786,638, forward strand). Ensembl gene ENSG00000199901.
Homologues: Orthologues: chimpanzee Y_RNA (97% identical), macaque Y_RNA (96% identical), guinea pig Y_RNA (93% identical). Paralogues in human: RNY3 (91% identical), Y_RNA (90% identical), RNY3P1 (89% identical), Y_RNA (89% identical), Y_RNA (88% identical), Y_RNA (87% identical), RNY3P9 (86% identical), Y_RNA (86% identical), Y_RNA (85% identical), RNY3P11 (84% identical), RNY3P16 (84% identical), Y_RNA (84% identical), and 95 more.